FAS (Fas cell surface death receptor)
Diseases named in the same sentence as FAS in open-access papers (continued):
Sharing a sentence is not in itself a finding about the gene and the disease.
lung carcinoma (31 papers, 2010 to 2025). "Future studies should focus on functional analyses of FAS and its mutations in lung cancer cells to better understand how downregulation of FAS contributes to apoptosis evasion." (PMID 39416461, 2024). "While these studies have implicated FAS in cancer progression and response to therapy, studies exploring FAS gene expression and its potential role as a prognostic biomarker in lung cancer, particularly in NSCLC, are limited." (PMID 39416461, 2024). "Specifically, we have shown that FAS is significantly downregulated in lung cancer and characterized its mutational and methylation profiles." (PMID 39416461, 2024). "FAS signaling facilitates apoptotic cell death in lung cancer cells, and advanced lung cancer is associated with decreased expression of FAS in circulating CD8 + T cells." (PMID 32963220, 2020). "In various malignancies, including breast, prostate, and lung cancer, FAS expression is notably increased." (PMID 40839202, 2025). "For example, while FAS downregulation has been reported in lung cancer, there are also studies that show that can promote lung cancer growth in vivo." (PMID 39416461, 2024). "We have also shown that alterations in FAS are a rare event in lung cancer, occurring in 1.9% of all samples." (PMID 39416461, 2024). "Further, the potential modulation of FAS expression by patient characteristics such as age and smoking status in lung cancer context requires more detailed investigation." (PMID 39416461, 2024). "We used cBioportal to investigate the prevalence and types of genomic alterations of the FAS gene in lung cancer patients." (PMID 39416461, 2024). "The role of FAS and other factors in influencing lung cancer progression and metastasis deserves further investigation." (PMID 39416461, 2024). "One of the most important findings of this work is that FAS was significantly downregulated in lung cancer, both in LUAD and LUSC." (PMID 39416461, 2024). "FAS expression was subsequently investigated at the protein level in samples from 578 lung cancer patients to understand its protein-level expression." (PMID 39416461, 2024). "We therefore searched multiple databases (e.g., GENT2, GEPIA2, and UALCAN for gene expression; STRING and GeneMANIA for protein-protein interaction; etc.)to obtain a conclusive result about the role of FAS in lung cancer." (PMID 39416461, 2024). "Our analyses showed a significant enrichment of genes encoding for known apoptosis mediators, such as FAS and CASP9 genes in human A549-rtTA-OSKM cells or Bid in mouse L1475luc-rtTA-OSKM lung cancer cells." (PMID 39587064, 2024). "In this study, we performed data mining in online tumor databases to investigate the expression, methylation, alterations, protein interactions, co-expression and prognostic significance of FAS in lung cancer." (PMID 39416461, 2024). "The expression levels of the FAS protein across various lung cancer samples were investigated.From the dataset that comprised 578 samples, nTPM values of FAS protein in lung cancer samples ranged from 5.2 to 67.2." (PMID 39416461, 2024). "In lung cancer, the expression of FAS was found to be significantly downregulated (P < 0.001 and log2FC = -0.569 for GPL570; P < 0.001 and -0.263 for GPL96)." (PMID 39416461, 2024). "The downregulation of FAS was also validated in our in vitro analysis in three lung cancer cell lines, when compared against the normal bronchial epithelial cell line HBE." (PMID 39416461, 2024). "At the protein level, we observed variability in the nTPM levels of FAS protein in the lung cancer samples, ranging from 5.2 to 67.2, suggesting considerable heterogeneity in FAS protein expression across tumor samples." (PMID 39416461, 2024). "The expression, prognostic significance and molecular interactions of FAS in lung cancer was mined and analyzed using GENT2, GEPIA2, UALCAN, cBioPortal, STRING, GeneMANIA, UCSC Xena, Enrichr, and OSluca databases." (PMID 39416461, 2024).
lung carcinoma (continued). "The relative expression of FAS in lung cancer cell lines (H1299, H1993, A549) was significantly lower than the normal bronchial epithelial cell line (HBE), with GAPDH serving as the internal control." (PMID 39416461, 2024). "At the protein level, data from The Human Protein Atlas showed that in a sample of 578 lung cancer samples, the average nTPM of FAS was 21.7 (range: 5.2-67.2, median: 19.1)." (PMID 39416461, 2024). "Further studies are needed to investigate the clinical significance of FAS alterations in lung cancer and to explore the potential of targeting FAS for therapeutic intervention." (PMID 39416461, 2024). "Further studies are needed to determine how FAS protein levels correlate with clinical outcomes and treatment efficacy in lung cancer." (PMID 39416461, 2024). "FAS alterations were rare (1.9%) in lung cancer samples, with deep deletions being more common than missense mutations, which occurred mainly in the TNFR-like cysteine-rich domain and the death domain." (PMID 39416461, 2024). "This study provides valuable insights into the involvements and characteristics of FAS in lung cancer." (PMID 39416461, 2024). "Knocking down FAS promoted lung cancer cell growth by accelerating cell cycle, suggesting that bona fide tumor-suppressive functions of FAS in NSCLC." (PMID 32963220, 2020). "Our study revealed for the first time that FAS knockdown facilitates STAT3 activation in lung cancer cells." (PMID 32963220, 2020). "Knocking down FAS promoted lung cancer cells growth through NFkB activation-mediated enhanced IL6 secretion and subsequent STAT3 activation." (PMID 32963220, 2020). "Next, to investigate the effects of miR-196b-5p on the expression of FAS mRNA and protein, we transiently overexpressed miR-196b mimics in A549 and H292 lung cancer cells." (PMID 32963220, 2020). "Activated FAS signaling suppresses lung cancer cell growth in a mouse model through increasing TH9 cell differentiation." (PMID 32963220, 2020). "In our study, we found that upregulated miR-196b-5p promotes lung cancer cell growth by targeting known tumor suppressor, FAS, in NSCLC." (PMID 32963220, 2020). "Together, these results suggested that the FAS downregulation promotes lung cancer cell growth by activating the STAT3 signaling pathway." (PMID 32963220, 2020). "To further demonstrate underlying molecular mechanisms of FAS knockdown-mediated enhancement of IL6 expression, we investigated p65 protein nuclear translocation in FAS knockdown lung cancer cells." (PMID 32963220, 2020). "We found that miR-196b-5p promotes lung cancer cell proliferation and colony formation by directly targeting tumor suppressor, FAS." (PMID 32963220, 2020). "MAPK8 is associated with the production and elimination of reactive oxygen species (ROS), while FAS mainly participates in cellular apoptosis in lung cancer." (PMID 30497474, 2018). "Expression and alterations of BCL2L1, IGF1R, MAPK8, and FAS were investigated in lung cancer using TCGA database, and 4105 clinical samples provided by 13 studies were utilized in this study." (PMID 30497474, 2018). "It will also be important to examine whether the methylation status of FAS is tissue-specific and whether certain lung cancer subtypes exhibit unique epigenetic signatures that could provide therapeutic targets." (PMID 39416461, 2024). "Therefore, in this study, we performed data mining in online tumor databases to better understand the expression, prognostic significance and molecular interactions of FAS in lung cancer." (PMID 39416461, 2024). "We hypothesize that FAS gene expression is significantly altered in lung cancer compared to normal tissue and that genetic alterations, such as promoter methylation and mutations, could influence disease progression." (PMID 39416461, 2024). "The clinical implications of understanding FAS expression in lung cancer are significant." (PMID 39416461, 2024).
lung carcinoma (continued). "Thus, there is a need for more comprehensive and integrative approaches to understand the molecular and cellular mechanisms of FAS that drive lung cancer progression." (PMID 39416461, 2024). "FAS has been implicated in the development of various cancers, but its involvement in lung cancer has not been systematically characterized." (PMID 39416461, 2024). "An example of this mechanism is the expression of the FAS gene in lung cancer cells." (PMID 39769428, 2024). "Further in vitro and in vivo studies are needed to explore the role of FAS in lung cancer metastasis, particularly to assess whether its downregulation affects the invasive potential of lung cancer cells." (PMID 39416461, 2024). "In conclusion, we have successfully characterized the role of FAS in lung cancer." (PMID 39416461, 2024). "Nevertheless, the findings of this study may provide valuable insight into the role of FAS in the pathogenesis of lung cancer." (PMID 39416461, 2024). "It is also possible that there are other confounding factors or co-occurring genes that affect lung cancer progression and patient survival, which could limit the prognostic significance of FAS expression in the cancer." (PMID 39416461, 2024). "It is also difficult to determine whether these genomic changes have a significant clinical impact in lung cancer, as the frequency of these FAS alterations was low." (PMID 39416461, 2024). "This study aims to better understand the expression patterns, promoter methylation, genomic alterations, and potential protein-protein interactions of FAS in lung cancer, which could provide new insights into its role as a prognostic biomarker." (PMID 39416461, 2024). "However, the role of FAS in lung cancer subtypes, particularly LUAD and LUSC, remains poorly understood concerning its gene expression, mutational landscape, and clinical relevance." (PMID 39416461, 2024). "Future studies should aim to investigate whether FAS expression in combination with other apoptotic markers could provide a more accurate prognostic model for lung cancer." (PMID 39416461, 2024). "While FAS plays a role in several types of cancer, its role in lung cancer may be more context-dependent or its prognostic significance may be overshadowed by other factors." (PMID 39416461, 2024). "To further investigate the functions of FAS in lung cancer cells proliferation, colony formation, and cell cycle, we knocking down FAS in A549 and H292 cells by two independent siRNAs since both cell lines have relatively higher FAS expression than other lung cancer cell lines." (PMID 32963220, 2020). "Since IL6 could promote STAT3 signaling pathway, we further evaluated IL6 expression after knocking down FAS in lung cancer cells." (PMID 32963220, 2020). "As expected, we observed that increased IL6 expression in FAS knockdown lung cancer cells." (PMID 32963220, 2020). "Moreover, we assessed the death risk of lung cancer patients using 4 target genes related to let-7a-5p, including BCL2L1, IGF1R, MAPK8, and FAS." (PMID 31508368, 2019). "For the inhibitory effect of RBM5 on lung cancer, in current studies, it is reported that RBM5 modulates apoptosis by regulating the alternative splicing of apoptosis-associated pre-mRNAs, such as CASP2 and FAS/CD95." (PMID 23721095, 2013). "Interestingly, the authors’ previous studies found the combining effects of FAS and FASL polymorphisms on risk of esophageal squamous cell carcinoma and lung cancer." (PMID 23951214, 2013). "Finally, in vivo studies are needed to assess whether modulation of FAS expression could have therapeutic potential in lung cancer, either as a direct target or in combination with existing treatments." (PMID 39416461, 2024). "Indeed, FAS knockdown promoted nuclear translocation of p65 protein compared to those control cells, suggesting that NFkB activation by FAS knockdown is the main cause of increased IL6 expression in lung cancer cells." (PMID 32963220, 2020).
lung carcinoma (continued). "To further demonstrate the relationship between STAT3 and FAS in NSCLC, we knocking down STAT3, FAS, or both of them in lung cancer cells." (PMID 32963220, 2020). "The expression levels of the FAS were investigated in three lung cancer cell lines and a normal cell line." (PMID 39416461, 2024). "The lack of significant prognostic value for FAS in this study, despite it being downregulated in lung cancer, highlights an important aspect of cancer research — the importance of negative findings." (PMID 39416461, 2024). "Despite successfully demonstrating the reduced expression of the FAS gene in lung cancer, survival analysis revealed no prognostic significance of the gene in lung cancer." (PMID 39416461, 2024). "Knocking down FAS activates NFkB signaling and subsequent IL6 secretion, resulting in phosphorylation of signal transducer and activator of transcription 3 (STAT3) to promote lung cancer cell growth." (PMID 32963220, 2020). "The expression of exosomal let-7a-5p was detected in pneumoconiosis, and all potential target genes related to exosomal let-7a-5p were predicted, among which four target genes related to lung cancer were selected for downstream analysis, including BCL2L1, IGF1R, MAPK8, and FAS." (PMID 30497474, 2018). "This suggests that although downregulation of FAS is a common feature of lung cancer, it may not be a reliable predictor of disease outcome." (PMID 39416461, 2024). "Nevertheless, none of these studies were conducted in lung cancer cells, and it remains unclear whether FAS plays a role in lung cancer cell progression and metastasis." (PMID 39416461, 2024). "The lack of prognostic significance in our study may indicate that while FAS plays a role in tumor initiation, its downregulation may not be critical for disease progression or metastasis in lung cancer." (PMID 39416461, 2024). "However, the expression, prognostic significance and molecular interactions of FAS in lung cancer have not been systematically studied." (PMID 39416461, 2024). "One possible explanation for the limited prognostic significance of FAS is that although the gene plays a role in the early stages of lung cancer development, its expression may not be critical for tumor progression or metastasis." (PMID 39416461, 2024). "Moreover, AXL and the other TAM receptors (TYRO3 and MERTK) have been reported as key mediator of chemoresistance in neuroblastoma through induction of EMT and in lung cancer through the regulation of mitogen-activated protein kinase (MAPK) and FAS signaling pathways." (PMID 34745951, 2021). "Interestingly, conditioned medium from FAS knockdown cells markedly increased STAT3 phosphorylation, suggesting that increased IL6 expression by FAS knockdown is responsible for STAT3 activation in lung cancer cells." (PMID 32963220, 2020). "High expression of BCL2L1 elevated lung cancer patients death risk [hazard ratio (HR) and 95% confidence intervals (CI) = 1.60(1.38–1.86)], but no similar correlations were found in IGF1R, MAPK8, and FAS." (PMID 31508368, 2019). "Considering FAS mediates external cell death signaling, we speculate that manipulation of FAS expression without external cell death signal may not impact on the cell death rate of lung cancer cells." (PMID 32963220, 2020). "The distribution of FAS and FASL genotypes in our cohorts corresponds to the frequencies reported on Caucasian subjects in a lung cancer study, but we could not provide any evidence that FAS and FASL gene polymorphism are linked with risk for GC or HRAG in Caucasians." (PMID 21864388, 2011).
prostate carcinoma (28 papers, 2008 to 2025). A carcinoma that arises from epithelial cells of the prostate gland. "However, expression of a constitutively active form of p65 NFκB causes apoptosis in prostate cancer cells, in part due to increased expression of the death receptor CD95 (FAS) and enhanced levels of toxic BH3 domain proteins." (PMID 36408163, 2022). "Our results give support to this hypothesis as they showed an increased expression of FADD and CASP 8 genes in both breast and prostate cancer cell lines and for the prostate cell lines also of FAS gene, associated with the external apoptosis pathway." (PMID 29444163, 2018). "It is involved in the alternative splicing of the apoptosis regulatory gene FAS, overexpressed in breast, ovarian, and prostate cancers, and contributes to tumor drug resistance." (PMID 38645664, 2024). "Further, functional inactivation of USP2a results in decreased FAS protein with reinforced apoptosis of prostate cancer cells." (PMID 34489969, 2021). "The FAS gene is upregulated at an early stage in multiple cancers, including breast 26, stomach 27 and prostate cancers 28; its expression is positively correlated with poor survival." (PMID 33723286, 2021). "In particular, both the CCNA2 gene and FAS gene are activated by the androgen receptor that is the therapeutic target of prostate cancers." (PMID 32164534, 2020). "New evidence has identified FAS expression as a molecular signature of highly aggressive metastatic prostate cancer." (PMID 22641253, 2012). "In the present study, our results demonstrate that green tea polyphenols induce apoptosis in prostate cancer cells by activating the FAS death receptor/caspase-8 pathway and inhibiting the p-Akt/p-BAD cell survival pathway." (PMID 23285096, 2012). "Increasing the LIP by supplying Fe2+, as holo-TF or FAS, sensitized prostate cancer cells to VC." (PMID 36139668, 2022). "FAS mRNA and FAS protein are both significantly overexpressed in prostate carcinomas." (PMID 22641253, 2012). "Finally, FAS (also called Apo1 or CD95) plays a central role in the physiological regulation of programmed cell death and has been implicated in the pathogenesis of various malignancies and diseases of the immune system including prostate cancer." (PMID 27597880, 2016). "Based on the correlation between the copy number losses of PTEN, FAS, PAPSS2 and PSA recurrence and with the current quest for an improved biomarker, it is recommended that the molecular function and translational implication of PTEN, FAS, and PAPSS2 loss in prostate cancer are further investigated." (PMID 25679447, 2015). "PAWR induces apoptosis by activation of the FAS pathway, and co-parallelly by inhibition of NFKB in certain cancer cells, specifically prostate cancer." (PMID 27871224, 2016). "In prostate cancer, HIPK3-mediated FADD phosphorylation is crucial for FAS-induced apoptosis." (PMID 40280416, 2025). "Similarly, SFN-induced apoptosis by FAS/CD95 has been reported for human leukaemia and human prostate cancer cells." (PMID 28864908, 2018).